SNX5 (sorting nexin 5)
Description:
Involved in several stages of intracellular trafficking. Interacts with membranes containing phosphatidylinositol 3-phosphate (PtdIns(3P)) or phosphatidylinositol 3,4-bisphosphate (PtdIns(3,4)P2). Acts in part as component of the retromer membrane-deforming SNX-BAR subcomplex. The SNX-BAR retromer mediates retrograde transport of cargo proteins from endosomes to the trans-Golgi network (TGN) and is involved in endosome-to-plasma membrane transport for cargo protein recycling. The SNX-BAR subcomplex functions to deform the donor membrane into a tubular profile called endosome-to-TGN transport carrier (ETC) (Probable). Does not have in vitro vesicle-to-membrane remodeling activity. Involved in retrograde transport of lysosomal enzyme receptor IGF2R. May function as link between endosomal transport vesicles and dynactin (Probable). Plays a role in the internalization of EGFR after EGF stimulation (Probable). Involved in EGFR endosomal sorting and degradation; the function involves PIP5K1C isoform 3 and is retromer-independent. Together with PIP5K1C isoform 3 facilitates HGS interaction with ubiquitinated EGFR, which initiates EGFR sorting to intraluminal vesicles (ILVs) of the multivesicular body for subsequent lysosomal degradation (Probable). Involved in E-cadherin sorting and degradation; inhibits PIP5K1C isoform 3-mediated E-cadherin degradation. Plays a role in macropinocytosis.
Tractability: Antibody: UniProt places it where antibodies can reach, with high confidence; its Gene Ontology location is reachable by antibodies, with medium confidence. PROTAC: ubiquitination databases record sites on it; its protein half-life has been measured.
Gene: Protein-coding gene on chromosome 20 (17,941,597 to 17,969,022, reverse strand). Ensembl gene ENSG00000089006.
Subcellular location: Endosome; Early endosome; Early endosome membrane; Cell membrane; Cytoplasmic vesicle membrane; Cytoplasm; Cell projection, phagocytic cup; Cell projection, ruffle
Subcellular location (Human Protein Atlas): Cytosol; Vesicles
Pathways (Reactome):
Vesicle-mediated transport: Golgi Associated Vesicle Biogenesis
Gene Ontology:
Molecular function: cadherin binding; dynactin binding; phosphatidylinositol binding; protein binding; D1 dopamine receptor binding; phosphatidylinositol-3,5-bisphosphate binding; phosphatidylinositol-4-phosphate binding; phosphatidylinositol-5-phosphate binding
Biological process: endosome membrane tubulation; pinocytosis; positive regulation of DNA-templated transcription; positive regulation of insulin receptor signaling pathway; retrograde transport, endosome to Golgi; regulation of macroautophagy; endosomal transport; epidermal growth factor catabolic process; intercellular transport; intracellular protein transport; negative regulation of blood pressure
Cellular component: cytoplasmic side of early endosome membrane; cytoplasmic side of plasma membrane; cytosol; early endosome; early endosome membrane; endosome; endosome membrane; macropinocytic cup; perinuclear region of cytoplasm; plasma membrane; retromer complex; retromer, tubulation complex; tubular endosome; brush border; cytoplasm; cytoplasmic vesicle membrane; phagocytic cup; ruffle
Genetic constraint (gnomAD): Loss-of-function variants: 24 observed, 33.88 expected, observed/expected ratio (o/e) 0.71, 90% interval 0.51 to 1. The upper end of that interval is the gene's LOEUF score, 1, which puts it in group 4 of 6, group 1 being the genes least tolerant of losing a copy. Missense variants: 299 observed, 293.01 expected, observed/expected ratio (o/e) 1.02, 90% interval 0.93 to 1.12. Synonymous variants: 118 observed, 113.33 expected, observed/expected ratio (o/e) 1.04, 90% interval 0.9 to 1.21.
Homologues: Orthologues: chimpanzee SNX5 (100% identical), macaque SNX5 (99% identical), rat Snx5 (99% identical), mouse Snx5 (98% identical), guinea pig SNX5 (96% identical), dog SNX5 (84% identical), tropical clawed frog snx5 (81% identical), zebrafish snx5 (72% identical), Drosophila melanogaster Snx6 (51% identical), Caenorhabditis elegans snx-6 (49% identical), Drosophila melanogaster Snx1 (18% identical), Caenorhabditis elegans snx-1 (14% identical). Paralogues in human: SNX6 (64% identical), SNX32 (61% identical), SNX2 (20% identical), SNX1 (20% identical), SNX7 (18% identical), SNX9 (17% identical), SNX30 (17% identical), SNX8 (17% identical), SNX18 (16% identical), SNX33 (15% identical), SNX4 (14% identical), SNX11 (10% identical), and 3 more.
Diseases named in the same sentence as SNX5 in open-access papers:
SNX5 is named in the same sentence as 34 diseases in open-access papers, as found by Europe PMC text mining. Sharing a sentence is not in itself a finding about the gene and the disease. The quoted sentences say what the papers report.
viral infection (6 papers, 2020 to 2025). "Deletion of SNX5 makes cultured cells more susceptible to viral infection, and mice deficient in SNX5 have a high lethality after infection with several human viruses." (PMID 34722550, 2021). "Deletion of SNX5 in mice models results in increased susceptibility to multiple human viral infections and enhances lethality after infection." (PMID 33374212, 2020). "Following viral infection, SNX5 interacts with Beclin1 and the Class III phosphatidylinositol 3-kinase (PI3KC3) complex 1 (PI3KC3-C1), which includes ATG14, at early endosomes containing virions." (PMID 40144551, 2025). "These exciting results reveal that SNX5 thereby plays an important role in the immune response following viral infections." (PMID 33374212, 2020). "Following viral infection, SNX5 initiates autophagosome biogenesis by localizing to virion-containing early endosomes." (PMID 33374212, 2020). "Deletion of SNX5 increases cell susceptibility and mortality to viral infection in vitro, indicating that enhancing SNX5 expression and autophagy induction may be crucial for the immune response to viral infections." (PMID 40144551, 2025). "In addition, it has been reported that SNX5 stimulates autophagy during viral infection." (PMID 35207596, 2022). "Overexpression of SNX5 can inhibit the virus-induced activation of nuclear factor kB (NF-kB) and Type-I interferons (IFN) regulatory factor 3 (IRF3), which may lead to a decrease in the cell’s ability to fight viral infection." (PMID 35898490, 2022). "Moreover, they found that SNX5 could interact with PI3KC3-C1 and promote its activation at endosomes and therefore contributes to the initiation of autophagy during viral infection." (PMID 34722550, 2021).
head and neck squamous cell carcinoma (5 papers, 2020 to 2025). A squamous cell carcinoma that arises from any of the following anatomic sites: lip and oral cavity, nasal cavity, paranasal sinuses, pharynx, larynx, and salivary glands. "It suggests a SNX5 regulation of apoptosis in the progression of head and neck squamous cell carcinoma." (PMID 36612066, 2022). "However, recent investigation revealed differential expression levels of SNX5 in head and neck squamous cell carcinoma where higher expression levels of SNX5 were correlated with tumor progression, aggressiveness, and poor patient survival." (PMID 36612066, 2022). "However, SNX5 decreases the FBW7-mediated oncoproteins degradation to promote head and neck squamous cell carcinoma progression." (PMID 35024436, 2022). "In head and neck squamous cell carcinoma (HNSCC) SNX5 interacts with the E3 ligase F box proteins, thereby blocking FBW7 mediated ubiquitination of oncoproteins including c-Myc, NOTCH, and cyclin E1." (PMID 33374212, 2020). "For example, FBW7, an E3 ubiquitin ligase, interacts with SNX5 to reduce the ubiquitination and degradation of cancer-associated proteins such as c-Myc, NOTCH1, and Cyclin E1, thereby promoting the progression of head and neck squamous cell carcinoma (HNSCC)." (PMID 40144551, 2025). "In head and neck squamous cell carcinoma (HNSCC), SNX5 was also significantly elevated." (PMID 36528556, 2022).
hepatocellular carcinoma (5 papers, 2021 to 2025). A malignant tumor that arises from hepatocytes. "Our previous research shows that SNX5 predicts poor prognosis and promotes hepatocellular carcinoma progression by modulating the EGFR-ERK1/2 signaling pathway." (PMID 35024436, 2022). "Moreover, VPS35 knockdown weakened SNX5-induced EGFR degradation in hepatocellular carcinoma (HCC)." (PMID 37950040, 2024). "Overexpression of SNX5 was documented to inhibit intracellular degradation of EGFR, while in hepatocellular carcinoma (HCC), SNX5 was witnessed to activate the EGFR-ERK1/2 pathway by lowering the circulation rate of EGFR in the endosomal network which leads to an increased amount of EGFR8,9." (PMID 35715463, 2022).
glioma (4 papers, 2021 to 2023). A benign or malignant brain and spinal cord tumor that arises from glial cells (astrocytes, oligodendrocytes, ependymal cells). "Consistently, our data also showed that the upregulation of SNX5 was associated with enhanced glioma progression, indicating the potential of SNX5 as a target for developing glioma treatment." (PMID 33982667, 2021). "Exosome-derived circ-0001445 was shown to be taken up by glioma cells and to act as a sponge for miR-127-5p, thus upregulating the expression of sorting linker protein 5 (SNX5), which promotes glioma migration and invasion." (PMID 38020906, 2023). "Circ-0001445 entering glioma cells can act as a sponge for miR-127-5p and upregulate the expression of sorting linker protein 5 (SNX5), which promotes glioma migration and invasion." (PMID 35999601, 2022). "Collectively, these results show that exosomal circRNA 0001445 promotes glioma proliferation, migration, and invasion through the miRNA-127-5p/SNX5 signaling pathway." (PMID 33982667, 2021). "Taken together, the results demonstrated that exosomal circRNA 0001445 acts as a pro-tumor regulator in glioma progression and that the effect of circRNA 0001445 was mediated by miRNA-127-5p/SNX5 signaling pathway." (PMID 33982667, 2021). "Intriguingly, glioma cell-derived exosomes increased the protein expression of SNX5 in glioma cells, which was reversed by the addition of miRNA-127-5p mimics." (PMID 33982667, 2021). "Moreover, our results indicated that the effect of exosomal circRNA 0001445 in glioma was mediated by miRNA-127-5p/sorting nexin 5 (SNX5) signaling pathway." (PMID 33982667, 2021). "Glioma-derived exosomal circRNA-0001445 significantly promotes proliferation and inhibits the apoptosis of glioma cells via the miRNA-1275p/SNX5 signaling pathway." (PMID 34957113, 2021). "Functionally, miRNA-127-5p mimic could significantly downregulate both protein and mRNA expression of SNX5 in glioma cells." (PMID 33982667, 2021).
thyroid cancer (4 papers, 2018 to 2022). "Previous studies showed that loss of SNX5 stabilizes internalized growth factor receptors to promote thyroid cancer progression." (PMID 35024436, 2022). "Loss or decreased expression SNX5 promotes thyroid cancer progression." (PMID 31568528, 2019). "Given that SNX5 is a negative prognostic marker for liver cancer and plays a role in promoting thyroid cancer progression by stabilizing growth factor receptors, C11orf42 may contribute to these pathological processes via its interaction with SNX5." (PMID 33426787, 2021). "Finally, reduced expression of SNX5 was shown recently to be related to promotion of thyroid tumorigenesis and SNX5 expression studies can be used to support a pathology diagnosis of thyroid cancer." (PMID 30473937, 2018).
lung carcinoma (3 papers, 2019 to 2022). "And the knockout of SNX5 gene significantly changed tumor morphology and slowed down tumor growth in nude mice with lung cancer." (PMID 34041868, 2021). "SNX5, a macropinocytosis related gene, has been knocked out for the first time in human lung cancer cells and shown to be very important for tumor growth rate and tumor morphology in vivo, for the first time linking extracellular ATP with macropinocytosis in tumorgenesis and metastasis." (PMID 31582910, 2019).
breast carcinoma (2 papers, 2015 to 2024). "Among the other genes that we linked to late stage disease, little is known about their potential roles in other cancers although NUDT2 has previously been shown to be upregulated in human breast carcinomas whereas SNX5 is upregulated in papillary thyroid carcinomas." (PMID 25889361, 2015). "We observed that the TRs of certain genes, such as SNX5 and NGEF, strongly correlated with the estrogen receptor (ER) phenotype in breast cancer." (PMID 39349823, 2024).
gastric cancer (2 papers, 2022 to 2024). A primary or metastatic malignant neoplasm involving the stomach. "MNX1-AS1, PLRG1, and SNX5 gene expression levels were found to be higher in 70 primary gastric cancer samples after genome-wide expression profiling." (PMID 35831348, 2022). "Validation of the RIPK genes through GEPIA identified 8 genes (NRP1, MNX1, SSRP1, PRDX2, PLRG1, LGALS4, SNX5 and FXYD3) which are highly expressed in stomach cancer were significantly down-regulated in PRU treated samples." (PMID 35831348, 2022). "Specifically, 8 genes (NRP1, MNX1AS1, SSRP1, PRDX2, PLRG1, LGALS4, SNX5 and FXYD3) were found to be highly expressed in stomach cancer tissues compared to normal tissues." (PMID 35831348, 2022). "Specifically, 8 genes NRP1, MNX1, SSRP1, PRDX2, PLRG1, LGALS4, SNX5 and FXYD3) which are highly expressed in stomach cancer were significantly down-regulated in PRU treated samples." (PMID 35831348, 2022).
papillary thyroid carcinoma (2 papers, 2015 to 2022). "High expression of SNX5 was demonstrated in well-differentiated papillary thyroid carcinoma, and co-expression of SNX5 and caspase-2 was also found in thyroid epithelial cells." (PMID 35715463, 2022).
respiratory failure (2 papers, 2013 to 2025). The significant impairment of gas exchange within the lungs resulting in hypoxia, hypercarbia, or both, to the extent that organ tissue perfusion is severely compromised. "Targeted inactivation of the Snx5 gene led to neonatal mortality caused by respiratory failure, in which differentiation of alveolar epithelial type I cells was impaired, while maturation of alveolar epithelial type II cells was intact." (PMID 23526992, 2013). "In order to investigate the causes of respiratory failure in Snx5-/- mice, we examined the palate, trachea, esophagus, diaphragm, intercostal muscles, and heart." (PMID 23526992, 2013). "In order to further investigate the causes of respiratory failure in the Snx5-/- mice, we examined whether the differentiation of alveolar epithelial type I cells was intact." (PMID 23526992, 2013). "Here, we report that disruption of the Snx5 gene in mice (Snx5-/- mice) resulted in partial perinatal lethality; 40% of Snx5-/- mice died shortly after birth due to cyanosis, reduced air space in the lungs, and respiratory failure." (PMID 23526992, 2013). "Furthermore, in mice, SNX5 knockout leads to respiratory failure." (PMID 40457499, 2025). "Collectively, these results suggested that the respiratory failure of Snx5-/- mice was not due to malformations of the palate, trachea, esophagus, diaphragm, intercostal muscles, or heart." (PMID 23526992, 2013). "This suggests that deletion of Snx5 did not affect the maturation of alveolar epithelial type II cells and that the respiratory failure in the Snx5-/- mice was not due to functional defects of alveolar epithelial type II cells." (PMID 23526992, 2013).
Chlamydia infection (1 paper, 2017). "Depletion of SNX5/6 facilitates Chlamydia infection, thus SNX5/6 function as a restriction factor and IncE functions to suppress this inhibition." (PMID 29263922, 2017).
Cyanosis (1 paper, 2013). Bluish discoloration of the skin and mucosa due to poor circulation or inadequate oxygenation of arterial or capillary blood. "Neonatal Snx5-/- mice showed significant breathing defects associated with cyanosis and reduced pulmonary air space in the lungs at birth." (PMID 23526992, 2013).
dilated cardiomyopathy (1 paper, 2024). Cardiomyopathy which is characterized by dilation and contractile dysfunction of the left and right ventricles. "These proteins are closely related to dilated cardiomyopathy (LMNA and MYH9), fibrosis (Vim), monocarboxylate transport (Slc16a1), vascular function (Cbx3 and Hnrnpn1), and endocytic trafficking (Snx5)." (PMID 39502510, 2024).
Hypertension (1 paper, 2021). The presence of chronic increased pressure in the systemic arterial system. "Another study has indicated that SNX5 depletion can result in hypertension in normotensive mice." (PMID 34946851, 2021).
mesothelioma (1 paper, 2025). A usually malignant and aggressive neoplasm of the mesothelium which is often associated with exposure to asbestos. "Additionally, in mesothelioma, the AS factors HSPA1A (heat shock protein family A member 1A) and DDX3Y (DEAD-box helicase Y) regulate the AS of SNX5 (sorting nexin 5), affecting immune evasion and bone metastasis." (PMID 41268214, 2025).
oral cancer (1 paper, 2022). "Furthermore, the higher mRNA expression level of SNX5 was positively related to the different advanced pathological stages of OSCC, and was found in oral cancer from Oncomine database." (PMID 36528556, 2022).
osteosarcoma (1 paper, 2023). A usually aggressive malignant bone-forming mesenchymal neoplasm, predominantly affecting adolescents and young adults. "To this end, we performed double knockout (KO) of SNX1 and SNX2 (SNX1-2), and SNX5 and SNX6 (SNX5-6), in the human osteosarcoma cell line HT1080." (PMID 37322239, 2023).
respiratory distress syndrome (1 paper, 2013). "Moreover, elucidation of the function of Snx5 in lung development may provide targets for novel therapeutic strategies for the prevention and treatment of respiratory distress syndrome." (PMID 23526992, 2013).
synucleinopathies (1 paper, 2025). "In particular, SNX5 seems to be a promising novel target for the development of a neuroprotective treatment for PD and related synucleinopathies." (PMID 40457499, 2025). "Our findings suggest that SNX5 is involved in the regulation of the trafficking and toxicity of αSyn and could be a promising target for future development of neuroprotective therapies for PD and related synucleinopathies." (PMID 40457499, 2025). "Therefore, SNX5 appears to be a target of therapeutic intervention for synucleinopathies." (PMID 40457499, 2025).
thyroid tumor (1 paper, 2021). A benign or malignant neoplasm affecting the thyroid gland. "Enhanced expression of SNX5 was also exported in thyroid tumor." (PMID 34041868, 2021).